BRCA1 (BRCA1 DNA repair associated)
Diseases named in the same sentence as BRCA1 in open-access papers (continued):
Sharing a sentence is not in itself a finding about the gene and the disease.
breast cancer (continued). "We also generated isogenic pairs of BRCA1-deficient and -reconstituted human breast cancer cell lines MDA-MB-436 and HCC1937." (PMID 35641483, 2022). "Linkage studies in families with breast cancer at an early age suggest that mutation in BRCA1 and BRCA2 is linked to breast cancer predisposition." (PMID 35163783, 2022). "In contrast, deletions overlapping SULT1A1 suggested a decreased breast cancer risk (HR = 0.73, 95% CI 0.59-0.91) in BRCA1 pathogenic variant carriers." (PMID 36203093, 2022). "According to previous research, BRCA1/2 mutation carriers had a higher risk of mortality from breast cancer (HR 1.44, 95% CI: 1.05–1.97) and distant metastases (HR 1.82, 95% CI: 1.05–3.16) than sporadic/BRCA-negative individuals." (PMID 35409110, 2022). "Germline pathogenic variants in the Breast Cancer Genes 1 (BRCA1) and 2 (BRCA2) are responsible for Hereditary Breast and Ovarian Cancer (HBOC) syndrome." (PMID 36230639, 2022). "Germline mutations in DNA repair genes are predictive for hereditary types of cancer, especially BRCA1/2 in breast cancer or deleterious mutations in RAD51C/RAD51D/BRCA1 in ovarian cancer." (PMID 36531044, 2022). "Results from Phase II clinical trials show that antibodies targeting PD-L1 in combination with PARPis exhibit a good response against germline BRCA1/2-mutated breast cancer and ovarian cancers." (PMID 35326571, 2022). "Research performed over more than a decade in South Africa led to the development of a rapid BRCA1/2 founder/recurrent mutation assay for improved clinical management of breast cancer and associated co-morbidities." (PMID 35664315, 2022). "The BRCA1 gene (Case 1), located at 17q21, is a tumor suppressor gene, and its mutation can be observed in breast cancer and ovarian cancer." (PMID 36686750, 2022). "The study aims to develop a personalized risk management decision support tool for carriers of a pathogenic variant (BRCA1 or BRCA2) who underwent breast-conserving therapy for unilateral early-stage breast cancer." (PMID 36580360, 2022). "It exerts an antiproliferative effect in breast tissues of healthy women and reduces mammary cancer development in mice, further attesting to its potential merit as a cancer risk-reducing agent in germline BRCA1/2 mutation carriers." (PMID 35701800, 2022). "Our data suggest that EZH2 inhibition can be combined with ATM inhibition to provoke toxic DSBs leading to apoptosis-mediated cell death in BRCA1-deficient breast cancer cells." (PMID 35715861, 2022). "In BRCA1, one variant, c.2521C > T (p.Arg841Trp), was associated with a decreased risk of breast cancer (OR 0.67 (0.52–0.87), p = 0.0027)." (PMID 35585550, 2022). "In these cells, the somatic loss of 53BP1 leads to olaparib resistance due to the partial restoration of HR repair activity, decreasing the response of BRCA1-deficient mouse mammary tumors to the inhibitor." (PMID 36497275, 2022). "FUSCC has developed an NGS-based pipeline for BRCA1/2 mutation testing to better recognize possible BRCA germline mutations in patients with breast cancer and to alert affected relatives." (PMID 35380032, 2022). "In summary, HRT remains contraindicated prior to prophylactic rrBSO in BRCA1/2 carriers due to an increased breast cancer risk." (PMID 35685436, 2022). "This work explored the mechanism of the effect of breast-cancer susceptibility gene 1 (BRCA1) on the metabolic characteristics of breast cancer cells, including the Warburg effect and its specific signaling." (PMID 36193432, 2022).
breast cancer (continued). "Along the same lines, evidence from epidemiological studies also supports progesterone-mediated upregulation of the RANK pathway in the predisposition to breast cancer among women with a BRCA1 mutation." (PMID 35418083, 2022). "In patients with breast cancer with the BRCA1 and BRCA2 pathogenic variants with luminal breast cancer in stage II, RRBM + RRBSO had a very modest impact on survival compared with surveillance." (PMID 36580360, 2022). "The genetic medicine for primary breast cancer patients with BRCA1/2 germline mutation is accelerating rapidly in Japan." (PMID 35191009, 2022). "Four recurrent variants were discovered among unrelated African-descended breast cancer patients: BRCA1:c.3331_3334delCAAG, BRCA1:c.211A>G, BRCA2:c.1389_1390delAG, and PALB2:c.1671_1674delTATT." (PMID 35353237, 2022). "The risk of germline copy number variants (CNVs) in BRCA1 and BRCA2 pathogenic variant carriers in breast cancer is assessed, with CNVs overlapping SULT1A1 decreasing breast cancer risk in BRCA1 carriers." (PMID 36203093, 2022). "Our data also revealed the potential mechanism leading to CIN elevation in breast cancer with BRCA1 germline mutation." (PMID 34403063, 2022). "Fingerprint patterns (six or more loops) and predominant BRCA1 gene variants: forty-eight per cent (48%) of breast cancer participants had six or more loops and c.34311A>C." (PMID 36942145, 2022). "In two clinical trials conducted in patients with breast cancer treated with neoadjuvant monotherapy using cisplatin, the incidences of complete regression in patients with BRCA1 germline mutations were 100% and 83%, respectively." (PMID 36613648, 2022). "Oocyte or embryo freezing is the basic method of fertility preservation in breast cancer patients, including BRCA1/2 gene mutation carriers." (PMID 35887761, 2022). "According to reports of familial breast cancer cases, these oncoproteins are notorious for inducing mutations in BRCA1 gene, due to the functional interaction that exists between E7 and the BRCA1 gene." (PMID 35419411, 2022). "Historically, the synthetic lethality achieved through PARP inhibition in BRCA1/2 mutated breast cancer represents the ideal scenario for DDR inhibitor monotherapy; however, PARP inhibition is applicable outside of BRCA1/2 mutated cancers." (PMID 35747808, 2022). "In our initial study of Wwox in human breast cancer cells, we reported Wwox interaction with Brca1 and upregulated HR/SSA pathways in Wwox-deficient cells." (PMID 35409089, 2022). "Breast cancer susceptibility gene 1 (BRCA1) is one of the most frequently mutated tumor suppressor genes in human breast cancers." (PMID 35453307, 2022). "In conclusion, our study provides evidence that CNVs contribute to the variability in breast cancer risk among BRCA1 and BRCA2 pathogenic variant carriers." (PMID 36203093, 2022). "The patients with pathogenic/likely pathogenic variants in the non-BRCA1/2 genes mainly developed OC alone compared to the other groups that also developed breast cancer or other tumors (p = 0.001)." (PMID 36555431, 2022). "On the other hand, based on the significant PARP1 trapping capacity, talazoparib has been clinically employed in breast cancer patients with germline mutations of BRCA1/2 and other types of cancer that contain impaired DNA damage responses." (PMID 36497275, 2022). "This study evaluated single nucleotide polymorphism of the BRCA1 gene and finger dermatoglyphic patterns in relation to tumour characteristics in breast cancer participants." (PMID 36942145, 2022). "In summary, we explored the molecular subtypes of breast cancer in relation to BRCA1 gene variants and fingerprint patterns." (PMID 36942145, 2022). "In this study, however, HER2-enriched breast cancer recorded the highest total frequency of BRCA1 mutations of 10 (Annex 3) followed by triple-negative." (PMID 36942145, 2022).
breast cancer (continued). "Previous research has demonstrated that the BRCA1/2 deleterious variant frequency in BBC (29.6%) is significantly higher than the rate in unselected breast cancer (5.4%)." (PMID 36324133, 2022). "BRCA1 germline mutation carriers have a 37.9% cumulative risk of developing breast cancer by the age of 70 years, and the risk is 36.5% for BRCA2 germline mutation carriers, which is approximately 10 times higher than that in the general population." (PMID 35380032, 2022). "Recent work from our group and others has highlighted histone methyltransferase EZH2 (Enhancer of zeste homolog 2) as a promising target in BRCA1-deficient breast cancer." (PMID 35715861, 2022). "BRCA1, the first breast cancer susceptibility gene identified, is responsible for 5–10% of total breast cancers." (PMID 36497409, 2022). "Three breast cancers (one BRCA1, two BRCA2) developed allele-specific LOH upon recurrence, associated with a significant increase in HRD score." (PMID 36344544, 2022). "The main objective of this study was to identify potential phytocompounds (ligands) from the aqueous extract of Solanum torvum unripe fruits for breast cancer susceptibility protein belonging to BRCA1 gene." (PMID 34643844, 2022). "Despite the protective effects, BRCA1/2 germline carriers are in a unique clinical conundrum as the use of OCPs possesses a theoretical increased risk of breast cancer." (PMID 35685436, 2022). "Here we have presented a brief overview of the experimental and epidemiologic evidence suggesting that dysregulation of the progesterone-mediated RANK signaling pathway plays a critical role in the pathogenesis of BRCA1-associated breast cancer." (PMID 35418083, 2022). "The present study aimed at and reports on the relationship between the single nucleotide polymorphism of BRCA1 gene and finger dermatoglyphic patterns in breast cancer patients." (PMID 36942145, 2022). "Our in vivo study shows that the combined treatment with GSK126 and AZD1390 confers stronger anti-tumor activity than either inhibitor alone in BRCA1-deficient mammary tumors in mice, although the effect on progression-free survival was not strong." (PMID 35715861, 2022). "The sample set consisted of 67 primary and recurrent tumors from 13 BRCA1/2 germline mutation carriers with breast cancer and 14 BRCA1/2 germline mutation carriers with ovarian cancer." (PMID 36344544, 2022). "For example, breast cancer cells with deficiencies in HR proteins (such as BRCA1) can repair their DNA by either relying on other highly expressed HR-related proteins (such as RAD51 or PARP1) or backup DNA repair pathways such as alt-NHEJ23." (PMID 35610507, 2022). "We elucidated clinical characteristic and genomic analyses in germline BRCA1 or BRCA2 mutated breast cancer in Korean women." (PMID 35151316, 2022). "Mutations in BRCA1/2 confer high-penetrance susceptibility to breast and ovarian cancers, increasing the risk of developing breast cancer by 49–57% and ovarian cancer by 18–40%." (PMID 36741696, 2022). "Prevalence of somatic and/or germline pathogenic variant in BRCA1/2 and in other homologous recombination-related genes in breast cancers." (PMID 35158866, 2022). "We chose to identify shared neoantigens in BRCA1-related breast cancer because of its characteristic mutational signatures suggesting a pattern in mutational events within the group." (PMID 36298462, 2022). "Many experts assume that given the equal proportion of BRCA1 versus BRCA2 mutated breast cancers, and approximately 20% of BRCA1 and 80% of BRCA2 PV are associated with ER+ breast cancers, 50% of all BRCA1/2 mutated breast cancers are of ER+/HER2- subtype." (PMID 35158866, 2022). "A previous study had shown that a mouse Brca1 allele with a premature stop codon at an analogous human 5382 position predisposes mice to breast cancer." (PMID 36346676, 2022). "The mutant form of the SNPs of BRCA1 gene has been reported to be associated with the risk of breast cancer development." (PMID 36942145, 2022).
breast cancer (continued). "Metastatic breast cancer patients with a germline BRCA1 or BRCA2 mutation treated with PARPi have better outcomes in terms of PFS compared to standard chemotherapy." (PMID 35740616, 2022). "In another study, we were able to show that RXRα and PPARγ are overexpressed in BRCA1 mutated breast cancer cases and predict prognosis." (PMID 35406808, 2022). "In a study of 200 cases of Asian origin on breast cancer patients living in the USA, three in four Vietnamese patients were identified with the mutation c.5251C > T in BRCA1." (PMID 35205313, 2022). "The identification of targeted treatment strategies for BRCA1-deficient breast cancer is a current emphasis of preclinical research and clinical practice." (PMID 35715861, 2022). "According to statistics, 20% to 40% of hereditary breast cancers can be attributed to harmful mutations in BReast CAncer gene 1 (BRCA1) and BReast CAncer gene 2 (BRCA2)." (PMID 35402620, 2022). "All the three patients who developed OC and breast cancer with a germline BRCA1 mutation had a breast cancer diagnosis (median age, 42 years) before the onset of OC (median age, 62 years)." (PMID 36555431, 2022). "Approximately 5-10% of breast cancer cases are associated with the hereditary mutation of BRCA1 and BRCA1 genes." (PMID 36232989, 2022). "A translational study of the BRCA1 L1780P missense mutation is required to better understand breast cancer in Korean patients." (PMID 35626017, 2022). "In human cells, a battery of genes including the breast cancer susceptibility genes BRCA1 and BRCA2 work to favor most DSB repair towards error-free pathways." (PMID 36530474, 2022). "In earlier studies, tumours in BRCA1 mutation carriers were found to be less sensitive to taxane-based chemotherapy than tumours of sporadic breast cancer patients." (PMID 34929424, 2022). "Our study shows that in triple-negative and BRCA1/2-mutated breast cancer, MYC utilizes yet another strategy to promote immune evasion, namely by expulsion of virtually all tumor-infiltrating immune cell populations." (PMID 36323660, 2022). "It was estimated that the cumulative breast cancer risk for a 70-year-old woman is up to 87% for BRCA1 and 84% for BRCA2 mutation carriers with corresponding ovarian cancer risks up to 68% and 30%, respectively." (PMID 36246618, 2022). "This study sought to analyze the relationship between the single nucleotide polymorphism of BRCA1 gene and finger dermatoglyphic patterns in breast cancer patients and the potential usefulness of that information." (PMID 36942145, 2022). "As PARP1, the breast cancer susceptibility proteins BRCA1 and BRCA2 also stabilize stalled replication forks." (PMID 36350633, 2022). "Germline mutations causing functional deficiency in BRCA1/2 (gBRCA1/2) are found in about 5% of unselected patients with breast cancer." (PMID 34467476, 2022). "BRCA1/2 are breast cancer susceptibility genes that are involved in DNA repair and transcriptional control." (PMID 35409110, 2022). "Therapy resistance was linked to loss and amplification of the BRCA1 gene causing inferior survival of breast cancer patients." (PMID 36362151, 2022). "The first identified breast-cancer-predisposing genes BRCA1 and BRCA2 are responsible for about 25% of HBOC." (PMID 35625741, 2022). "The presence of BRCA1/BRCA2 gene mutations is associated with a cumulative risk of breast cancer at age of 70 of more than 60%, and the probability of developing this malignant tumor throughout life varies in the range of 41–90%." (PMID 35626173, 2022). "Differences between patients with breast cancer have been reported before relating to hormone status, for example, BRCA1 mutations are significantly enriched in TNBC." (PMID 34979999, 2022).
breast cancer (continued). "Another study demonstrated that DEGs and PPI networks are affected by the BRCA1/2 gene mutation in breast cancer samples." (PMID 35045088, 2022). "Breast cancer is the most common malignancy in individuals with a germline BRCA1/2 pathogenic variant, resulting in a lifetime risk ranging from 46% to 87%." (PMID 35608067, 2022). "This beneficial effect is lost upon adding a ligand as CORT, which is a negative regulator of BRCA1 expression that increases the risk for breast cancer." (PMID 36661673, 2022). "PVs of ATM and CHEK2 confers greater than 30% lifetime risk for breast cancer, but lower than that of BRCA1 and BRCA2, thus are regarded as moderate-high risk." (PMID 35323371, 2022). "RRBM-RRBSO was only the most effective risk-reducing strategy in patients with TN breast cancer under 40 years in stage I with the BRCA1 pathogenic variant and in patients aged 40-49 years with the BRCA1 pathogenic variant in exons 1-10." (PMID 36580360, 2022). "One study showed that high expression of DNMT3A was linked to promoter hypermethylation of ERα and BRCA1, and downregulation of ERα and BRCA1 in breast cancer patients." (PMID 35620052, 2022). "For a long time, breast cancer was regarded as a genetic disorder arising from mutations in key regulatory genes such as BRCA1 and BRCA2." (PMID 36076918, 2022). "For BRCA1/2 mutation-associated breast cancer, systemic therapy is given as appropriate to the stage and receptor status of a patient’s disease." (PMID 36344544, 2022). "We demonstrate that compared to monotherapies, combined PARP inhibition and STING agonism results in increased STING pathway activation, greater cytotoxic T-cell recruitment and enhanced dendritic cell activation in BRCA1-deficient breast cancer models." (PMID 36068244, 2022). "Assessment of clonogenic survival revealed a substantial decrease in the number of colonies by combined GSK126/AZD1390 treatment in BRCA1-deficient mouse mammary tumor cells, compared to vehicle control, as well as to single GSK126 or AZD1390 treatment." (PMID 35715861, 2022). "Approximately 62% of patients with breast cancer with a pathogenic variant (BRCA1 or BRCA2) undergo primary breast-conserving therapy." (PMID 36580360, 2022). "In recent years, olaparib has been approved for patients with breast cancer possessing mutated BRCA1/2 gene, male patients with metastatic castration-resistant prostate cancer, and patients with metastatic pancreatic cancer in Japan." (PMID 36267984, 2022). "It has been shown that BRCA1-deficient breast cancers exhibit higher abundances of tumor-infiltrating lymphocytes (TILs) and greater enrichment of T cell inflammation signatures than BRCA1-proficient breast cancers, with a wide range of variation." (PMID 35304461, 2022). "PALB2 (1.2%) was the most commonly mutated gene other than BRCA1/2 in Chinese breast cancer patients, while CHEK2 (2.82%), ATM (1.06%), and PALB2 (0.87%) were the most commonly mutated genes other than BRCA1/2 in European populations." (PMID 35494038, 2022). "Mutations of BRCA1 gene are the cause of 50–80% risk of breast, 40% ovarian cancer and in 40–50% of familial site-specific breast cancers." (PMID 35395863, 2022). "In the general male population, the lifetime risk of developing breast cancer is 0.1%; whereas in BRCA1 mutations it is 1.2% by the age of 70, rising to 6.8% in the case of BRCA2." (PMID 35303741, 2022). "Recent results have suggested that BRCA1-associated basal-like breast cancers originate from luminal progenitor cells instead of basal stem cells." (PMID 35118379, 2022). "This option can also be considered for women with a BRCA1/2 mutation who underwent a mastectomy for breast cancer and who are taking Tamoxifen as adjuvant therapy." (PMID 35683509, 2022).